IL10 (interleukin 10)
Diseases named in the same sentence as IL10 in open-access papers (continued):
Sharing a sentence is not in itself a finding about the gene and the disease.
tumor (continued). "IL-10 is well known for its immunoregulatory properties and is associated with poor prognosis in certain tumour contexts." (PMID 35565201, 2022). "CD209 (DC-SIGN), MARCO, and RELN genes function in the downregulation of the immune system through IL10 and inhibitory tumor-associated macrophage mechanisms, respectively." (PMID 34349241, 2022). "IL-4, IL-10, and IL-13 signaling, along with significantly elevated tumor-associated transcription factor abnormalities, upregulation of IL-17 and Hif-1a pathways, and glucose metabolism pathway, was enriched in Mac3, which pointed to M2 characteristics." (PMID 35874770, 2022). "The transfection of tumor cells with IL-10 or another systemic therapy of IL-10 suppressed the tumor growth and caused tumor rejection." (PMID 34152493, 2022). "Reactive astrocytes and tumor-associated macrophages, which lack phagocytotic activity, secrete IL-10, which has anti-inflammatory properties (by inhibiting the expression of MCH—major histocompatibility complex class II and IFN-γ)." (PMID 35205842, 2022). "Both IgG4 and tumor IL-10 are associated to shorter recurrence free survival (RFS) and overall survival (OS) in TNBC." (PMID 35255925, 2022). "Conditional deletion of NRP2 from tumor‐associated macrophages impaired the clearance of apoptotic tumor cells, which was associated with decreased expression of IL‐10 and TGF‐β and enhanced antitumor immune responses." (PMID 34861108, 2022). "On the contrary, Th2 associated cytokines such as IL-4, IL-6 and IL-10 support tumor growth and suppress cellular immunity." (PMID 35565378, 2022). "Specific deletion of IL-10 in Tregs or reconstitution of IL-10 receptor deficient CD8+ T cells showed tumor reduction." (PMID 35806328, 2022). "These tumor-associated macrophages (TAMs) secrete anti-tumor cytokines IL-6, IL-8 and IL-10 and matrix metalloproteinases (MMPs) which regulates neo-vasculogenesis in TME." (PMID 36253762, 2022). "For example, tumor-associated MSCs are reported to modulate the expression of cysteinase via the IL-10/STAT3 signaling pathway, thereby inhibiting the production of cysteine by DCs and suppressing the proliferation of naïve T cells." (PMID 36439438, 2022). "Together, this evidence suggests that IL-10 plays a pivotal role in the crosstalk between TAMs and immune cells during the tumor-associated immune response, and IL-10 maintains a potent target potential in anti-tumor therapies." (PMID 35327584, 2022). "Both cytokines have pro- and anti-tumor properties, being IL-10 widely associated with worse prognosis, not only in solid tumors but also hematological malignancies." (PMID 36497475, 2022). "In the TME, tumor-associated regulatory immune cells secrete various immunosuppressive cytokines, such as interleukin 10 (IL-10) and transforming growth factor beta (TGF-β), which inhibit immune cell activation." (PMID 36066630, 2022). "The main inflammatory factors associated with tumours include interleukin 6 (IL-6), interleukin 10 (IL-10), interleukin 1β (IL-1β), tumour necrosis factor alpha (TNF-α) and C-reactive protein (CRP)." (PMID 36482346, 2022). "Tumor-associated macrophages exhibit a high and sustained expression of B7-H4 and secrete a large amount of IL-10." (PMID 36514159, 2022). "On the contrary, M2 macrophages release anti-inflammatory cytokines, such as TGF-β, IL-10, and IL-13, and have been implicated in tissue healing and tumor progression." (PMID 36072957, 2022). "IL-10 deficiency diminished the Treg-mediated immunosuppression by suppressing neuropillin expression in Treg cells in mouse tumor models." (PMID 35371055, 2022). "These cells promote tumour invasion and metastasis through the production of matrix metalloproteinases and various chemoattractants, and also express TGF-β and IL-10, which stimulates the activity of regulatory T-cells and tumour-associated macrophages (TAMs)." (PMID 35512031, 2022).
tumor (continued). "This is supported by our multi-variant analysis where only stage and tumor IL-10 were predictive of shorter OS." (PMID 35255925, 2022). "Deletion of NRP2 in tumor‐associated macrophages was reported to result in decreased production of IL‐10 and TGF‐β following exposure to apoptotic cells." (PMID 34861108, 2022). "Tregs are believed to suppress the excessive immune response by expressing cytotoxic T-lymphocyte associated protein 4 (CTLA4) and secreting IL-10 and transforming growth factor beta (TGFβ), thereby promoting the immune escape of tumor cells." (PMID 35433424, 2022). "Meanwhile, M2 macrophages are associated with the proliferation and repair of tumor cells by secreting anti-inflammatory mediators like IL-10, TGF-β, and vascular endothelial growth factor (VEGF), among others." (PMID 36544764, 2022). "Tumor associated macrophages influence tumor progression through secretion of cytokines such as IL-10, INF-γ and CCL5." (PMID 36338755, 2022). "M2 type TAM secrete IL-10 and IL-13, and they are associated with killing and encapsulation of parasites, Th2 activation, tissue remodeling, and tumor induction and growth." (PMID 36293435, 2022). "Myeloma-associated macrophages also are a major source of IL-6, IL-10 and IL-1β that help in tumor proliferation and survival." (PMID 35172851, 2022). "Tumors often stimulate tumor-associated macrophages (TAMs) to display an immunosuppressive M2 phenotype, which supports tumor growth through the production of cytokines such as IL-10, instead of the anti-tumorigenic M1-like phenotype." (PMID 34158861, 2021). "The presence of IgA+ plasma cells expressing PD-L1 and IL-10 within the tumour environment has been linked with poor T cell immunity in human prostatic and liver cancers." (PMID 34732892, 2021). "Consistently, mice with specific deletion for β-catenin in CD11c+ cells exhibit reduced numbers of IL-10-producing Tregs intratumorally, which is associated with enhanced anti-tumor CD4 and CD8 T cell response." (PMID 34988072, 2021). "In the course of tumor development, M1 polarized macrophages infiltrated by tumor usually exhibit an IL-12 high IL-10 low phenotype, which promote the immune reaction and cause tumor cell division." (PMID 33391402, 2021). "Such researches indicate the repercussions of IL-10 deficiency to understand tumour-promoting inflammation and IL-10's crucial role in inflammation control." (PMID 34336101, 2021). "VEGF, β-catenin and PGE2 production by tumour cells and IL-10 secretion by tumour-associated macrophages have been shown to inhibit DC function and/or recruitment." (PMID 34885021, 2021). "While some studies have suggested that IL-10 can suppress tumors, others have suggested that tumor-associated elevation of IL-10 can suppress the anti-tumor immune response of the host." (PMID 33912464, 2021). "(Th) 2 cells release cytokines such as IL-4, IL-5, and IL-10, and Tregs cells cause immune-suppression, thus eventually supporting tumor growth." (PMID 34439380, 2021). "For example, DC-ASGPR can cause DCs to secrete IL-10 and negatively regulate the anti-tumor effects of DCs." (PMID 34588987, 2021). "IL-10, alone or in concert with IL-6, causes the upregulation of macrophage B7-H4 expression, which is responsible for the suppression of tumor-associated antigen-specific T cell immunity." (PMID 33418996, 2021). "Increased IL-10+ B cell numbers in ME can also be associated by increased numbers of Foxp3+ Tregs, which are independently associated with tumour progression or reduced patient survival." (PMID 34298847, 2021). "We quantitated serum levels of IL-10, which was elevated in tumor-bearing WT compared to IDO deficient mice." (PMID 34867973, 2021). "Tumor associated macrophages secrete immunosuppressive cytokines, such as interleukin-10 (IL-10) and transforming growth factor- β (TGF- β), can promote the growth and development of tumor." (PMID 34349038, 2021).
tumor (continued). "HIFU constructed an inflammatory TME with concentration gradients of the chemokines CXCL1/KC and IL-10, which was attributable to the proinflammatory response caused by the necrosis of tumor cells and the release of necrotic debris." (PMID 34715854, 2021). "Tumor-associated DCs (TADCs) can secrete numerous types of cytokines, such as IL-10 and TGF-β1 that inhibit T cell activation and promote tumor cell growth." (PMID 33407095, 2021). "Research has associated IL-10 deficiency with the increased production of pro-inflammatory cytokines, which promote tumor growth in mice." (PMID 33925400, 2021). "Tumour and tumour-associated cells produce and secrete various immunosuppressive factors to inhibit NK cell activation, including interleukin (IL)-6, IL-10, transforming growth factor-β (TGF-β), and prostaglandin E2 (PGE2)." (PMID 34306099, 2021). "Since tumor-associated myeloid cells can inhibit immune cell functions, the observed decrease in Il-4 and Il-5 together with a tendency of Il-10 in TR2myKO mice suggests a possible reduced polarization of T cells." (PMID 34868988, 2021). "The cytokines, such as CCL5 and IL10, will also recruit regulatory T cells (Treg) to the tumor site, and appears to be negatively associated with CD8 + T cell infiltration." (PMID 34141607, 2021). "Tumor-associated Tregs secretes IL10 and TGF-β, which inhibit cytotoxic T cells and NK cells and shape-up an immunosuppressive milieu." (PMID 33579265, 2021). "MDSCs expressed lower levels of anti-inflammatory Arg1, Il-10, Ccl17, and Ccl22, but produced higher levels of angiogenic factors compared to tumor-associated macrophages." (PMID 33441138, 2021). "It has been described to mediate the expression of IL-10 by cytotoxic cells and B cells and polarization of tumor-associated macrophage." (PMID 34026621, 2021). "They even observed a high level of anti-IL-6R mAb and MDSCs (they inhibit tumour progression) in IL-10-deficient mice." (PMID 34336101, 2021). "Reinartz derived a signal network model involving ovarian cancer cells and tumor associated macrophages (TAMs) linking IL-6, IL-10, and leukemia inhibitory factor (LIF) as cytokines that activate signal transducer and activator of transcription 3 (STAT3)." (PMID 34503128, 2021). "Investigations into the role of IL-10 have been mainly restricted to PD-1 expression on tumor-associated dendritic cells (DCs) and bone marrow-derived DC." (PMID 34827481, 2021). "Shb deficiency reduced Ifng and increased Il10 gene expression, suggesting an immunosuppressive tumor microenvironment relative to the wild type situation, since IFNγ is known to enhance and IL-10 to suppress immune responses." (PMID 34768912, 2021). "Another study on colorectal cancer tissue showed that low IL-10 levels in tumor cells are associated with worse prognosis, and with metastasis and invasion." (PMID 34832887, 2021). "So far, studies point towards a pro-tumorigenic role for most of the obesity-associated cytokines, whereof some, i.e., TNF-α, IL-6, and IL-10, also seem to induce activities inhibiting tumor progression." (PMID 34944905, 2021). "Immune suppressive and tumor-promoting action of IL-10 was supported by finding that IL-10 deficiency enhanced the efficacy of DC-based immunotherapy, reduced MDSC and Treg levels in the TME, and promoted Th1-type antitumor responses in mice." (PMID 35008550, 2021). "Down-regulation of granzyme B is a feature of intra-tumoral, as opposed to peri-tumoral, NK cells and correlates with expression of IL-10-positive tumour-associated macrophages." (PMID 33995362, 2021). "In this study, I found that direct tumor and tumor associated macrophage inhibition should be the actual reason of the efficacy of IL-10." (PMID 33912464, 2021). "Tumor-associated Mφs secrete a plethora of anti-inflammatory, immunosuppressive cytokines, such as IL-10 and TGF-β, which inhibit T-cell infiltration into and activation in the tumors." (PMID 34103524, 2021).
tumor (continued). "Tang demonstrated that hypomethylation of CpG islands within the IL-10 gene in GC tumours and adjacent tissue was associated with decreased OS, thus linking increased IL-10 expression with poor prognosis." (PMID 34944729, 2021). "This is consistent with a recent report that elevated IL-10 levels caused by anti-PD-1 mAb treatment were also found in an animal tumor model." (PMID 34769278, 2021). "As classic immunosuppressive factors, the increase of TGB-β and IL-10 is often accompanied by immune effector cell function inhibition and the increase of tumor-associated macrophage (TAMs) infiltration." (PMID 33968889, 2021). "In GC, IL-10 is secreted by both tumour-associated macrophages (TAMs) and Treg cells, although many immune effector cells produce IL-10 to some extent." (PMID 34944729, 2021). "IL-4, IL-10 and chemokines recruit circulating monocytes leading to generation of tumor associated macrophages (TAM)." (PMID 33923976, 2021). "Although this subset is associated with tumor progression, IL10 expression by this cluster was limited, implying that its suppressive function is unclear." (PMID 34880348, 2021). "Introduction of anti-IL10 antibody partially blocked proliferation induced by the supernatant, supporting a causative link between IL-10 and tumour proliferation." (PMID 34944729, 2021). "In fact, IL-10 production by tumor-associated macrophages in various cancers has been shown to correlate with disease progression and decreased survival." (PMID 34944793, 2021). "As the most crucial component in TME, tumor-associated macrophages (TAMs) can secrete various mediators such as cytokines (IL-10) and growth factors that promote tumor growth, invasion, and metastasis." (PMID 34055739, 2021). "IL-10-producing B cells, namely regulatory B cells, cause T cells to differentiate into Tregs and facilitate the spread and activation of Tregs, mediating tumor immune escape." (PMID 33767709, 2021). "In the TME, tumor-associated macrophages (TAM) promote neovascularization, tumor growth, and metastasis through cytokines (i.e., IL-6, IL-8, and IL-10) that clearly overlap with the SASP." (PMID 34206425, 2021). "In vitro and in vivo preclinical studies of pembrolizumab plus lenvatinib combinations decreased TGF-ß and IL-10 by suppressing tumor-associated macrophages, Tregs, and related tumor microenvironment constituents." (PMID 34956912, 2021). "In this case, increased tumor-related anti-inflammatory humoral factors like IL-10 or Tumor Growth Factor-beta (TGF-β) induce the loss of signal transducer CD3-ε chain (CD3-ε) in TIL." (PMID 33673332, 2021). "Pretreatment IL-10 concentration was associated with tumor burden, as the CSF cytology-positive and multi-lesion subgroups showed higher IL-10 levels." (PMID 33618687, 2021). "Intra-tumor injection of lentivral vectors encoding IL-10 shRNA reduces IL-10 expression and potentiates bone marrow derived dendritic cell vaccine efficacy in a mouse model of CRC." (PMID 34489941, 2021). "Reduced secretion of IL1β in a tumor decreases macrophage population and the associated interleukin-10 (IL10) production to enhance the relative proportions of dendritic cells as well as IL2 production." (PMID 34200642, 2021). "After these monocytes have committed to become tumor-associated macrophages, MAFs can continue to influence their behavior and promote IL-10 secretion in their unpolarized M0 and more committed M1 and M2 states as well." (PMID 34944793, 2021). "Inhibition of STAT3 signaling in microglia is associated with a shift to an anti-tumor phenotype characterized by an increase in co-stimulatory molecule expression, decreased production of IL-10, and increased expression of pro-inflammatory cytokine TNF-α." (PMID 34483843, 2021). "IL-10 producing tumor-associated macrophages (TAM) also accumulate in HCC and negatively correlate with granzyme B+ NK cells, indicating a possible inhibition of intratumoral NK cell function by TAM." (PMID 34445750, 2021).
tumor (continued). "Tumor-associated macrophages can be stimulated by IL-4, IL-10, or IL-13 and then migrate into tumor tissue, where they perform protumorigenic functions." (PMID 33292489, 2020). "Although previous reports suggest that tumor-associated IL-10 activity disrupts normal T-cell maturation, even in some SCID patients, overexpression of IL-10 appears to specifically interrupt T-cell maturation at an early stage." (PMID 32582141, 2020). "In this study, we found that the IL-10 rs1800872 G allele was associated with poorly differentiated tumor." (PMID 32744314, 2020). "When analyzing systemic IL-10 and IL-4 in regards to clinicopathological data and overall survival, only IL-10 demonstrated to be significantly associated with increased tumor stage and distant metastases." (PMID 32298379, 2020). "On the other hand, the expression of inhibitory molecules such as CTLA4, PD-1, and LAG3 on CD8+ T cells are promoted by IL-6 and IL-10, that produced by tumor cells and tumor-associated macrophages, in turn inhibit CD8+ T cells infiltration." (PMID 32208363, 2020). "We discovered an induced expression of IL-10 by HT and further revealed an enhanced tumor immunity associated with elevated IL-10." (PMID 32348468, 2020). "The use of STAT3 inhibitors in prostate cancer limited tumor-associated MDSCs and inhibited interleukin-1β (IL-1β), IL-10 and IL-6 synthesis by monocyte cultures." (PMID 32488850, 2020). "In a mouse model of HCC, both TGF-β and IL-10 have been found to be associated with tumor progression, and in vitro TGF-β has been found to promote the differentiation of Foxp3+CD4+ Tregs." (PMID 32488850, 2020). "In cancer, MDSCs induced the upregulation of IL-10 that downregulates macrophage IL-6 and IL-12 and tumor necrosis factor (TNFα) production, thereby polarizing tumor-associated macrophages (TAMs) toward a tumor-promoting M2 phenotype." (PMID 32983164, 2020). "TNF-α, IL-6 and IL-17 have known roles in tumor growth and promotion; IL-6 and IL-10 are produced by tumor-associated macrophages and create conditions of immune suppression and angiogenesis; IL-1β and IL-6 promote angiogenesis and tumor invasion." (PMID 33396710, 2020). "IL-10 production by tumor-associated macrophages can suppress the expression of the anti-tumor cytokine IL-12 by CD103+ cDC1s." (PMID 32486257, 2020). "Multiple studies associated the elevated levels of IL-10 produced by the tumor cells with different types of malignancies and aggressive behavior that should influence the surgical management." (PMID 32899735, 2020). "The inactivation of STK 11 increases production of G-CSF, CXCL7 and IL-6, which recruit tumor-associated neutrophils that in turn increase T-cell dysfunction via arginase A and IL-10 release." (PMID 33272262, 2020). "A similar finding was observed in tumor-associated macrophages, in which IL-4 synergized with IL-10 to activate the UPR via STAT3." (PMID 32714202, 2020). "In TME, hypoxia attracts tumor-associated macrophages (TAMs), which through IL-10 and IL-12 contribute to migration, invasion, and metastasis; moreover, adipocytes provide fatty acids as an energy source." (PMID 32974184, 2020). "Tumour cells, tumour-associated macrophages and infiltrating myeloid-derived suppressor cells can inhibit T cell function through release of TGFβ and IL-10 - these cytokines repress T-bet expression and upregulate the pro-apoptotic factor Bim." (PMID 33027962, 2020). "In contrast, M2 macrophages, called tumor-associated macrophages (TAMs), release immunosuppressive cytokines, such as IL-10, to facilitate tumorigenesis." (PMID 32377504, 2020). "Mello and colleagues suggested that protein malnutrition leads to increased blood levels of interleukin-10, which is regarded as an anti-inflammatory (tumorigenic) cytokine and causes tumor-specific T-cell immunity suppression and promotes cancer growth." (PMID 32280472, 2020).